MMP7 (matrix metallopeptidase 7)
Diseases named in the same sentence as MMP7 in open-access papers (continued):
Sharing a sentence is not in itself a finding about the gene and the disease.
cancer (continued). "MMP-7 has been identified as a validated drug target and anti-target for cancer therapy." (PMID 37513440, 2023). "To gain insights into the molecular mechanisms underlying elaiophylin’s impact on migration and invasion, we performed western blot analysis to assess the protein expression of MMP-7 and MMP-2, two key matrix metalloproteinases associated with cancer cell migration and invasion." (PMID 37894684, 2023). "Interestingly, IL-17A, which is produced during inflammation, promotes cancer metastasis by inducing EMT in cancer cells via MMP7." (PMID 37555952, 2023). "Notably, the identification of some Mmps (Mmp1, Mmp2, Mmp7 and Mmp9) has been reported as Myb-regulated genes in cancer cells." (PMID 37701782, 2023). "Manipulation of MMP-7 expression or function may become a potential treatment strategy for various types of diseases, most notably cancer." (PMID 38203373, 2023). "Like other MMPs, MMP7 promotes cancer invasion by the proteolytic degradation of ECM proteins." (PMID 37513440, 2023). "On the other hand, downregulation of MMP-7 may result in clinically unacceptable side effects, the initiation of cancer, or deleterious alterations in disease progression." (PMID 37513440, 2023). "Thus, the biological process of MMP-7 plays a crucial role in local invasion, lymph-node, and distal metastasis of cancer cells." (PMID 37188722, 2023). "Interestingly, EUG decreases the level of MMPs released by cancer cells which indicates MMP-7-triggered release of eugenol can be a self-regulated mechanism." (PMID 36831488, 2023). "Some MMPs, including MMP-3 and MMP-7, are involved in the transport of cancer cells." (PMID 38203373, 2023). "Interestingly, the combination of the MMP-7 -181G allele with SNPs in TIMP-1, TGF-β1 or chymase genes in H. pylori–infected patients significantly increased the risk of cancer progression and poor survival." (PMID 35163805, 2022). "MMP-2 rs1053605 was not markedly related to LC incidence among the overall populations and Caucasians under three models, while MMP-7 rs11568818 was not related to the risk of certain cancer types in three models, such as BC, GC, and LC." (PMID 35574300, 2022). "Several studies have demonstrated that expression of MMP-7 protein may serve as a prognostic marker in multiple types of cancers." (PMID 35496040, 2022). "Moreover, OSppc for pan-cancer prognosis analysis was used to evaluate the prognostic role of MMP7 in different cancer types at the protein level." (PMID 35785154, 2022). "Moreover, it was previously demonstrated that the downregulation of MMP7 can inhibit proliferation, migration, and invasion of cancer cells." (PMID 35785154, 2022). "MMP-7 also cleaves cell surface receptors, such as E-cadherin, to promote cancer cell invasion." (PMID 35682569, 2022). "In addition, fibroblast growth factor receptors in cancer-related fibroblasts activate Stat-3 signaling, thereby inducing MMP-7 expression." (PMID 36776395, 2022). "Furthermore, the potential correlation between the genetic alteration of MMP7 and the prognosis across all TCGA cancer types was determined." (PMID 35785154, 2022). "Finally, 135 articles on MMP-2, MMP-7, and MMP-9 polymorphisms related to cancer risk were included in the meta-analysis, among which 36,530 were cases and 41,258 were controls." (PMID 35574300, 2022). "It is plausible that MMP-7 degraded IGFBP-3 in hypoxic condition to reduce cancer cell apoptosis." (PMID 35586209, 2022). "Significant associations between variants in the MMP-2, MMP-7, and MMP-9 and cancer risk." (PMID 35574300, 2022). "Therefore, in order to obtain more accurate conclusions, this integrative meta-analysis for evaluating the relations of MMP-2, MMP-7, and MMP-9 variants with the risk of cancer was conducted." (PMID 35574300, 2022). "Matrix metalloproteinase-7 (MMP-7) has been suggested as a prognostic marker in several cancers." (PMID 35496040, 2022).
cancer (continued). "Its biochemical characteristics make MMP7 a potential target in several types of cancers." (PMID 36009404, 2022). "In addition, it has been demonstrated that induced cell stress activates the phosphoinositide-3-kinase, ERK1/2, and p38 signaling pathways, which lead to the synthesis of MMP-7 through the transactivation of NF-κB and c-Jun in cancer cells." (PMID 34973082, 2022). "The studies showed that the overexpression of MMP7 is common for a wide variety of cancers." (PMID 36009438, 2022). "Concerning MMP7, rs11568818 A allele noncarriers were predisposed to considerably higher rates of G3-histological-grade cancer in all analyzed statistical models." (PMID 36009438, 2022). "In addition to that, in these papers, the relations between MMP-2, MMP-7, and MMP-9 polymorphisms and the risk of a variety of cancers were evaluated." (PMID 35574300, 2022). "PRDX6 may promote the occurrence and development of ICC by regulating Wnt7a/Mmp7 in cancer cells and Wnt7b/Ccnd2 in macrophages." (PMID 36209344, 2022). "MMP7 is expressed by epithelial tumor cells and has a key function in cancer progression." (PMID 35203586, 2022). "However, high levels of MMP-7 have been described in several types of invasive cancers, and the role of MMP-7 in mediating invasive capability in a dependent β-catenin way was reported in nonadherent Eker rat Tsc2−/− cells." (PMID 34944575, 2021). "We suggest that our findings reported here are most applicable to PCa tumors with a luminal PCS2 subtype, and perhaps a more aggressive luminal PCS1 subtype, and less relevant for cancers that already produce significant amounts of MMP-7 that can readily cleave the PSPN Complex components." (PMID 33809984, 2021). "MMP-7 sheds cell surface proteins, amplifying its role in diseases including cancer." (PMID 33918254, 2021). "Also, MMP-7 promotes cancer invasion through proteolytic cleavage of ECM proteins and by activating other MMPs, including proMMP-2 and proMMP-9." (PMID 34502094, 2021). "Gemcitabine and oxaliplatin are known to activate intrinsic cell death mechanisms, following DNA damage, and cancer cells are known to upregulate MMP-7 to attenuate the Fas/FasL based extrinsic pathway for apoptosis resulting in increased chemoresistance and evasion of death signaling." (PMID 33918254, 2021). "MMP-7 may also contribute to cancer progression by the activation of MMP-2 and -9, and two epithelial–mesenchymal transformation pathways (RTK/RAS and the β-catenin)." (PMID 33946534, 2021). "Moreover, the IHC assay showed that MMP7 protein expression was enhanced in cancer tissues compared with adjacent normal lung." (PMID 34167089, 2021). "However, deregulated expression and/or function of MMPs (including MMP7) can lead to angiogenesis, cancer invasion, and metastasis[37 ▶]." (PMID 32429632, 2020). "This could explain why MMP-7 has been described more in cancer, where disruption of the basement membrane leads to the ability of cancer cells to invade intact tissue." (PMID 33409288, 2020). "Additionally, higher MMP7 expression was found both in the cancer tissues and sera of colorectal patients compared with the control group, leading to distant metastasis of cancer cells." (PMID 31937294, 2020). "Knockdown of ARF expression in cancer cells decreased MMP-7 expression, but when ARF was over-expressed, MMP-7 accumulated in the nucleus where it could bind to the ARF protein." (PMID 33352765, 2020). "The present review discusses the involvement of two MMPs, MMP-2 and MMP-7, in cancer pathogenesis." (PMID 32751899, 2020). "Moreover, MMP-7, an enzyme involved in the cleavage of the Fas ligand, has been shown to play a significant role in various pathological processes, including cancer metastasis, fibrosis, and more." (PMID 32053892, 2020).
cancer (continued). "RT-PCR analysis of β-catGOF; Mll1−/− organoids confirmed a decreased expression of Gata4 and revealed a concomitant upregulation of Bmp4 and the secretory differentiation markers Mmp7 and Muc2, identifying Mll1 as an upstream regulator of Gata4/Bmp4-controlled cancer stemness and differentiation." (PMID 33349639, 2020). "As a unique member of this family, MMP-7 exhibits a wide spectrum of substrate specificity and potential for activating a cascade of MMPs, which indicates that it is a promising biomarker in tumorigenesis and cancer progression." (PMID 33005257, 2020). "Immunohistochemistry experiments have also indicated that cancer cells compared to the corresponding normal cells may express higher levels of MMP7 protein[40 ▶]." (PMID 32429632, 2020). "Furthermore, the upregulation of the beta-catenin pathway activates matrix metalloproteinase-7 (MMP-7) and c-Myc, responsible for promoting cell growth and invasion and progression of malignant tumors." (PMID 31191748, 2019). "MMP-7 activation is directly associated with APC, and it is well established that APC mutations are frequently implicated as among the first mutations that occurs in the disease history of colon polyps as they progress to cancer." (PMID 31200666, 2019). "Additionally, MMP7 is highly expressed in multiple human malignant tumors and is closely related to metastatic PDAC." (PMID 31428151, 2019). "Interestingly, several genes associated with cancer cells invasion were downregulated upon HPSE knockdown, including MMP1, MMP7, MMP10, MMP13, and CEACAM6." (PMID 31001480, 2019). "In our study, CD44 and MMP7 were both upregulated in our cancer-normal comparisons." (PMID 31211760, 2019). "MT-MMP, MMP3, MMP9, and matrilysin (MMP7) localize to adherens junctions to shed the E-cadherin ectodomain, producing a soluble fragment frequently increased in the serum of cancer patients." (PMID 31380370, 2019). "Previous studies have shown the role of β-catenin/MMP-7 in cancer invasion and progression." (PMID 31350432, 2019). "In addition, there were multiple genes induced that are involved with cell and organelle structure and function (PNCK, UBD, CDH2, HERC5) and importantly, genes associated with the prostate, AR (MMP7, CDH2, ENO2, IGFBP3) and cancer (IFIT3, IFI44L)." (PMID 29416764, 2018). "FOXC1 promoted metastasis of cancers by increasing expression of MMP7, NEDD9 and Snail." (PMID 29552326, 2018). "Once taken up by cancer cells, the MMP7-sensitive peptide linkers between these two parts could be cleaved, finally converting into a hydrogel inside the cancer cell." (PMID 30274177, 2018). "While we have come to understand perlecan’s role in forming tissue boundaries and how MMP-7 cleaves these boundaries to allow cancer cells to move through tissues knowledge of the cell surface components that interact with perlecan to influence PCa cell behavior long have remained elusive." (PMID 29740048, 2018). "Although most MMPs degrade their ECM substrates, MMP7 is expressed in many epithelial cell types and is reportedly expressed at high levels in multiple cancer types, including pancreatic, colon, and gastric cancers." (PMID 28757546, 2017). "In addition to ECM degradation, MMP7 promotes cancer invasion by converting inactive forms of other MMPs, such as MMP2 and MMP9, into active forms." (PMID 28757546, 2017). "Several investigations indicate that MMP-7 is a validated drug target related to cancer." (PMID 32961647, 2017). "On the basis of these results, we suggest that the anti-invasive activity of antcin-H is in part due to the inhibition of MMP-7 expression, which plays a critical role in cancer invasion and metastasis, through the suppression of ERK-mediated AP-1/c-Fos and C/EBP-β activities in RCC cells." (PMID 29234409, 2017). "Furthermore, the overexpression of the EMT marker vimentin and MMP7 suggests that cancer cell invasion in our tumouroids is an active process dependent on the proteolysis of the surrounding ECM." (PMID 28276469, 2017).
cancer (continued). "MMP-7 is a validated target for the development of small molecule drugs against cancer." (PMID 32961647, 2017). "MMP-7 is an assured rabble-rouser of aggressive behavior in numerous of cancers including CRC." (PMID 27166267, 2016). "Notably, MMP7 was detected primarily in malignant cells of cancer lesions, with the intensive staining at the cytoplasm and plasma membrane (arrows indicated)." (PMID 27356744, 2016). "Nonetheless, the finding that specific perlecan fragments were elevated in serum in conjunction with MMP-7 elevation in tissue suggests that there are fragments derived from perlecan that may be useful indices of cancer tissue invasion." (PMID 26862737, 2016). "Moreover, the concomitant elevation of MMP7 and ARF in nucleus is associated with the malignancy of cancer cells." (PMID 27356744, 2016). "Polymorphisms in promoter regions of MMP genes might be related to the susceptibility of digestive cancers, with a role in cancer development for MMP1 and MMP7, and a role of protection against cancer for MMP2 and MMP9." (PMID 25596746, 2015). "In addition, NOX2 siRNA inhibited basal NADPH oxidase activity, TPA-induced ROS production, MMP-7 expression, and cell invasion, indicating that NOX2 plays a critical role in induction of MMP-7 expression in invasive cancer cells." (PMID 26116564, 2015). "Also the areas under the curve were 0.821 for TIMP-1, 0.888 for COX-2 and 0.880 for MMP-7 statistically significant (p = 0 < 0.001) in the cancer group." (PMID 29201696, 2015). "It has also been implicated in cell motility and invasion via matrix metallopeptidase 7 (MMP7), and may stimulate cancer metastasis." (PMID 26555578, 2015). "MMP7 is a key member of this family that inherits the same properties as well as other specific features, which suggests that it is an affective biomolecule in tumorigenesis and cancer progression." (PMID 25919283, 2014). "Similar to other cancers, many authors aimed to assess the MMP7 prognostic role in GC survival." (PMID 25919283, 2014). "MMP7 is an established instigator of aggressive behavior in a number of cancer types including CRC." (PMID 24885920, 2014). "According to previous reports, p-STAT3 could interact with p-c-Jun to regulate MMP-1, MMP-7 or other genes expression in human cancers." (PMID 25070240, 2014). "Previous studies have suggested that Smad4 may regulate MMP7 expression in cancer, and we therefore examined the effect of transiently silencing Smad4 in oral squamous carcinoma cells by transfected siRNA." (PMID 25424420, 2014). "We speculated that the GAD1/β-catenin/MMP7 interaction affects cancer cell behaviors, such as cellular invasiveness and migration." (PMID 24261884, 2013). "MMP-7 is expressed at very low levels in the adult, and only in a few tissues; however, it has gained attention due to its presence in a variety of disease states including cancer and CKD." (PMID 24273653, 2013). "Overexpression of MMP-7 has been reported in several other malignancies, and its depletion with siRNA resulted in a significant decrease in the invasive potential of different cancer cell types." (PMID 24244164, 2013). "In addition, we identified that elevated levels of MMP-7 in cancer tissues are a strong and independent predictor of poor prognosis." (PMID 23408109, 2013). "P120ctn nuclear translocation could relieve Kaiso-mediated repression of several cancer-related genes, such as MMP7 or Wnt11." (PMID 24260200, 2013). "We then investigated MMP7 secretion, a downstream candidate of GAD1/β-catenin interaction, because MMP7 often is overexpressed in human cancer tissues and associated with cancer cell invasiveness by proteolytic cleavage of the ECM substrates and degradation of basement membrane proteins." (PMID 24261884, 2013).
cancer (continued). "MMP7 is a Wnt-targeting gene that has been detected in several cancers, such as prostate, colon, stomach, lung, and breast and degrades components of the extracellular matrix (ECM), including collagens (I, III, IV, and V), fibronectin, vitronectin, laminin, and elastin." (PMID 24261884, 2013). "It was reported that elevated expression of MMP7 enhanced the invasive ability of cancer cells." (PMID 24312338, 2013). "Finally, we investigated the roles of cyclin D1 and MMP7 in gland and cancer formation in the mouse, and assessed the relevance of Lef1 to human cancer by comparing expression levels in cancerous and normal endometrial tissues." (PMID 22792274, 2012). "It has been reported that MMP7 plays an essential role in cancer invasion and metastases." (PMID 22957092, 2012). "However, evidence is accumulating to suggest that MMP-7, like other MMPs, has also a major role in cancer, although it has also found to be expressed by oval cells in rats models." (PMID 23185381, 2012). "It has been speculated that MMP-7 expressed on the surface of carcinoma cells may cleave E-cadherin and facilitate the detachment of carcinoma cells from the site of primary tumor, although we did not see this inverse relationship of expression in our work." (PMID 22863036, 2012). "Moreover, elevated expression of MMP-7, -8, -9, and -11 have been described in PC tissues; two of these, MMP-7 and MMP-11, are strongly associated with poor cancer prognosis." (PMID 21625447, 2011). "This is an important question since MMP-7 is a secreted proteinase, and it is likely that its release from cancer cells could affect adjacent normal tissue." (PMID 20628524, 2010). "MMP7 is known to play an important role in cancer growth, and its up-regulation could be a key mechanism for cancer cells' escape from the immune surveillance." (PMID 21060876, 2010). "Our goal was to investigate the possibility that MMP-7 produced by cancer cells may have effects on adjacent normal epithelium." (PMID 20628524, 2010). "MMP7 (matrilysin), is a metalloproteinase with prometastatic function related to: 1) early tumor development, 2) metastatic potential and 3) clinical outcome in cancer." (PMID 19266094, 2009). "Finally, a small population of cancer cells expressed high levels of MMP7." (PMID 42079046, 2026). "We integrated analyzed the function of P4HA3 among 33 types of cancers, and found that P4HA3 was associated with proliferation markers (PCNA and MKI67), EMT markers (VIM, TWIST1, SNAI1, SNAI2, FN1 and CDH2), extracellular matrix (ECM) markers (MMP9, MMP7, MMP2 and MMP14)." (PMID 39504328, 2024). "In addition, since MMP7 can degrade E-cadherin, it is speculated that MMP-7 on the cancer cell membranes cleaves E-cadherin, allowing the cell to be detached from the primary cancer cell nests." (PMID 37814323, 2023). "Also, MMP-7 can act as a potential molecular marker for cancer diagnosis." (PMID 37513440, 2023). "Additionally, MMP-7 may act as an oncogenic protein that regulates the physiology of various cancers." (PMID 38203373, 2023). "Furthermore, trigonelline-mediated inhibition of MMP-7 led to downregulation of the Raf/ERK/Nrf2 signaling pathway, which is believed to play a crucial role in many mechanisms associated with the pathogenesis of various types of cancer." (PMID 37110693, 2023). "Since the interaction of SDC2 with MMP-7 is important to regulate cancer activity, and 50 nM of S2P showed anticancer activity both in vitro and in vivo, we further investigated whether 50 nM of S2-D and S2-FE could inhibit the cancer activity of HT29-SDC2 cells." (PMID 35682569, 2022). "However, no systemic pan-cancer analysis on the association between MMP7 and different cancers based on big clinical data is available." (PMID 35785154, 2022). "Additionally, EPE strongly limited invasion and MMP-7 secretion in MPM cancer cells." (PMID 33228230, 2020).